CCL4 (C-C motif chemokine ligand 4)
Diseases named in the same sentence as CCL4 in open-access papers (continued):
Sharing a sentence is not in itself a finding about the gene and the disease.
atherosclerosis (continued). "In summary, our data are in line with those of previous studies and imply that CCL4 might be the key regulator of atherosclerosis through the LXR pathway." (PMID 32911750, 2020). "Future studies may be conducted to further elucidate the complex mechanisms of CCL4 and to validate the novel anti-inflammatory strategy targeting CCL4 in other atherosclerosis animal models before potential clinical implications are drawn." (PMID 32911750, 2020). "Future studies should clarify whether CCR1 and CCR2, in addition to CCR5, could contribute to the beneficial effects of direct CCL4 inhibition on atherosclerosis." (PMID 32911750, 2020). "In addition to CCL5, CCL3 and CCL4 have also been reported to participate in the process of atherosclerosis." (PMID 32194402, 2020). "Given the potential contribution of both metabolic risk factors and inflammatory cytokines to the progression of atherosclerosis, the role of CCL4 could be important and complex both in vivo and in vitro." (PMID 32911750, 2020). "However, the current study simply showed the direct effects of CCL4 monoclonal antibody on the in vivo atherosclerosis." (PMID 32911750, 2020). "Taken together, our observations suggested the potential effects of CCL4 in the vulnerability of atheromas and the progression of atherosclerosis, which may be related to its role in the activation of macrophages, as well as endothelial cells." (PMID 32911750, 2020). "In this study, the direct inhibition of CCL4 could decrease circulating IL-6 and TNF-α levels, suggesting the potential modulation of downstream inflammatory cytokines by blocking CCL4 in atherosclerosis in vivo." (PMID 32911750, 2020). "The direct inhibition of CCL4 modified metabolic profiles, inhibited vascular inflammation, reduced the plaque area, and promoted a relatively stable plaque phenotype in an experimental model of atherosclerosis in vivo." (PMID 32911750, 2020). "This study aimed to investigate whether CCL4 inhibition could retard the progression of atherosclerosis." (PMID 32911750, 2020). "Our findings may help to clarify whether CCL4 could be a potential anti-inflammatory target for atherosclerosis." (PMID 32911750, 2020). "Taken together, these observations suggest the potential involvement of CCL4 in atherosclerosis." (PMID 32911750, 2020). "Clinically, circulating CCL4 levels are increased in patients with atherosclerosis." (PMID 32911750, 2020). "On the other hand, CCL4 could also be upregulated in atherosclerosis and myocardial infarction to enhance adhesion molecule expression and accelerate the vascular inflammation response." (PMID 27553774, 2016). "Therefore, exploring the interaction between CCL4 and mast cells may provide new insights into atherosclerosis treatment." (PMID 35509837, 2022). "Therefore, CCL2 and CCL4 are novel therapeutic targets for regulating atherosclerosis." (PMID 35509837, 2022). "In apolipoprotein E-deficient mice model, CCL4 antibody treatment reduced circulating IL-6 and TNF-α whereby the authors concluded that CCL4 inhibition seems to be a promising tool within the box of anti-inflammatory therapeutics in patients diagnosed with atherosclerosis." (PMID 36290379, 2022). "CCL4 may be a novel therapeutic target for modulating atherosclerosis." (PMID 32911750, 2020). "Therefore, inflammatory chemokines such as CCL4 might act as a possible node to link the presence of DM and atherosclerosis." (PMID 27553774, 2016). "The KGs of T cells involved in the effects of hawthorn on the PVAT microenvironment in atherosclerosis were CCL3, CCL4, MT2A, and MT1X." (PMID 40824771, 2025). "Our results were verified by qPCR for the selected cytokines involved in immune cell activation and migration (CCL2, CCL3, CCL4, CCL5, CX3CL1), representing potential therapeutic targets in atherosclerosis." (PMID 38256102, 2024).
atherosclerosis (continued). "The expression patterns of the major migration-driving chemokines MCP-1 (CCL2), MIP-1α (CCL3), MIP-1β (CCL4), RANTES (CCL5), and fractalkine (CX3CL1) in patients with atherosclerosis were of particular interest in this study." (PMID 38256102, 2024). "We then explored both bulk RNA-seq and scRNA-seq data to unravel the potential role of CCL4 and its receptor(CCR5) in the development of atherosclerosis and CAD." (PMID 39512689, 2024). "Based on the correlation criteria and correlation criteria value, CCL2, CCL4, TLR2, IL1B and PTPRC were identified as hub immune genes in atherosclerosis." (PMID 35509837, 2022). "Bioinformatic and correlation analyses of differentially expressed immune cells helped to identify CCL4, TLR2, IL1B, and PTPRC as hub genes in atherosclerosis formation and plaque progression." (PMID 35509837, 2022). "More exploration of CCL4 and CXCR4 secreted by PAT would enhance the understanding of the pathophysiological mechanism of atherosclerosis and facilitate its utilization as a biomarker and intervention target for atherosclerosis." (PMID 34552562, 2021). "Our findings are in line with previous research and further confirm the systemic effects of CCL4 antibody treatment on circulating IL-6 and TNF-α in in vivo experimental atherosclerosis." (PMID 32911750, 2020). "CCL4 and its receptor CCR5 were reported to be significantly induced in the infarct myocardium, vulnerable atherosclerosis plaques, advanced atherosclerotic lesions, and to be associated with a higher risk of stroke and cardiovascular events." (PMID 32923679, 2020). "In atherosclerosis, many studies have supported the role of the chemokine receptor CCR5 and its ligands CCL3, CCL4, and CCL5 in triggering the progression of atherosclerosis, particularly in later stages of plaque." (PMID 32346605, 2020). "Mediators involved in atherosclerosis (CX3CL1/fractalkine, CCL8, M-CSF, CXCL5, CCL4, HGF), tissue remodeling (MMP-12, MMP-1, MMP-10) and angiogenesis (VEGF-A) were also increased in AD." (PMID 28821884, 2017). "Given the critical role of inflammatory and immune cells in the aetiology of atherosclerosis and CAD, it is not surprising that CCL4 and CCR5 have been associated with this disease." (PMID 39512689, 2024). "In addition to CCL3, CCL4, and DUSP2, IL1B, known to be highly relevant in atherosclerosis, was highly upregulated in CM of HIV+CVD+ women." (PMID 36045343, 2022). "In addition, CCL4, TLR2, IL1B and PTPRC were considered to be immune marker genes in atherosclerosis development." (PMID 35509837, 2022). "Additionally, increasing IL-10, IL-4, IL-13, and TGF-β and reducing IL-1β, Il-6, TNF-α, CCL3, CCL4, and CCL5 can slow the progression of atherosclerosis." (PMID 32346605, 2020). "Among them, only CCR5 was related to the progression of atherosclerosis, as some of its ligands, such as CCL3, and CCL4, CCL5, could be detected in atheroma plaques." (PMID 32911750, 2020). "This review focuses on the emerging evidence for the multiple roles of CCL4-related mechanisms, including those of CCL4 and one of its major receptors, fifth CC chemokine receptor (CCR5), in both experimental and clinical DM and atherosclerosis cardiovascular diseases." (PMID 27553774, 2016). "On the other hand, although the role of CCR5, a receptor of CCL4, may be diverse in different experimental DM models, experimental evidence favored the involvement of CCR5 in the progression of atherosclerosis cardiovascular disease." (PMID 27553774, 2016). "CCL4-related mechanisms, including CCL4 and CCR5, might provide potential therapeutic targets in DM and/or atherosclerosis cardiovascular diseases." (PMID 27553774, 2016). "However, evidence now supports a role for CCR5 and its ligands CCL3 (MIP-1a), CCL4 (MIP-1b), and CCL5 (RANTES) in the initiation and progression of atherosclerosis." (PMID 22577254, 2012).
atherosclerosis (continued). "In addition, although the results show that CCL4 is more inclined in atherosclerosis, CCL4 does not appear to be significantly different in progression and regression of AS plaque." (PMID 40182401, 2025). "In conclusion, our study demonstrated that decreased expression of miR-24-3p and increased expression of miR-595 in patients with CAD may lead to progression of atherosclerosis plaque by regulating the expression of CCL3, CCL4, IL-1β, TNFαIP3, and NF-κBIα genes." (PMID 36381642, 2022). "Accordingly, future experimental and clinical studies are worthwhile to clarify if anti-CCL4 mechanisms, including direct blocking of CCL4 and/or of CCR5, could be a promising therapeutic approach to retard the development of DM, atherosclerosis cardiovascular diseases or both." (PMID 27553774, 2016). "However, the role of CCL4 has not been well-defined in atherosclerosis in vivo." (PMID 32911750, 2020). "In addition, high-dose CCL4 antibody treatments not only improved the metabolic profiles at least partially by upregulating LXR expression, but also reduced the circulating inflammatory cytokines, suggesting systemic anti-inflammatory effects on atherosclerosis." (PMID 32911750, 2020).
breast carcinoma (37 papers, 2015 to 2025). "The association of hepatocyte growth factor (HGF) with breast cancer was stronger in Estrogen Receptor (ER)-negative patients, while CASP8, CXCL11, MMP7, and C–C motif chemokine 4 (CCL4) were associated with ER-positive breast cancer." (PMID 40665092, 2025). "One previous Mendelian randomization analysis on cytokines found an association between genetically predicted CCL2, CCL4, and GROα and breast cancer." (PMID 36685922, 2022). "CCL2 and CCL5 play important roles in prostate cancer metastasis and drug resistance, while CCL4 is associated with the clinical characteristics of breast cancer." (PMID 33737938, 2021). "However, after adjusting for other comorbidities (obesity, T2D, and breast cancer), age, smoking, alcohol consumption, and ethnicity, MIP-1b/CCL4, TNFα, and VEGFα remained independently associated with HTN in our study cohort." (PMID 38541912, 2024). "We found that Groα/CXCL1 (obesity-associated), MIP-1b/CCL4 (obesity- and HTN-associated), TNFα (HTN-associated), and TGFβ1 and β2 (T2D-associated) were also significantly associated with breast cancer independently." (PMID 38541912, 2024). "Our study identified serum levels of MIP-1b/CCL4, TGFβ1, and TGFβ2 were independently associated with breast cancer." (PMID 38541912, 2024). "CCL4 is involved in the proliferation and metastasis of various cancers such as breast cancer and squamous cell carcinoma." (PMID 35296026, 2022). "The expression of TAM-derived MIP-1β or CCL4 chemokine relates to poor survival in breast cancer patients, potentiating breast cancer cell invasion and metastasis through increased myosin IIIA (MYO3A) gene expression." (PMID 32326073, 2020). "The essential role played by CCL4 in breast cancer metastasis has been reported in a previous study." (PMID 29599774, 2018). "Proteins involved in chemotaxis and inflammation, including CCL3, CCL4, CXCL11, and CCL23, were only found to be associated with long-term breast cancer risk after five years, suggesting the long-term effect of inflammation on breast cancer risk." (PMID 40665092, 2025). "In addition, medium produced in vitro by the EPS of human muscle cells and a combination of recombinant myokines CXCL1, IL10, and CCL4 also reduced the growth rate and induced cell death of breast cancer cells." (PMID 39518934, 2024). "The connection of MIP-1b/CCL4 with breast cancer was also more likely to promote tumor progression." (PMID 38541912, 2024). "The association of MIP-1b/CCL4, TGFβ1, and TGFβ2 and breast cancer were complicated." (PMID 38541912, 2024). "However, differentiated neutrophils exclusively expressed IL23, whereas the undifferentiated neutrophils solely expressed CCL4 when cultured in the breast cancer supernatant." (PMID 33049964, 2020). "In addition, we measured the concentrations of G-CSF, IL-1β, IL-6, CCL4 and TNFα in the plasma of the mice with breast cancer." (PMID 28178994, 2017). "In both the mammary carcinoma and fibrosarcoma cells, secretion of CCL2, CCL3, CCL4, and Cxcl10 was upregulated after poly(I:C) transfection." (PMID 35737804, 2022). "A more detailed analysis of 1100 patients with breast cancer (BRCA) revealed significant positive correlations between Il12b, Ifng, Ccl4, Ccl5, Cxcl9, and Cxcl10 gene expression levels and tumor infiltration of CD8+ T cells and M1 macrophages." (PMID 34446712, 2021). "Despite the demonstration that CCL4 secretion was lower than that of CCL5, CCL4 was found to be produced by breast cancer cells." (PMID 29299159, 2017). "Estrogen receptor (ER) negative breast cancers exhibit increased expression of inflammatory chemokines CCL2, CCL4, and CXCL8 compared to ER+ breast cancers and this correlates with the phenotype of the inflammatory infiltrate in the tumor." (PMID 28143493, 2017). "Furthermore, increasing serum levels of MIP-1b/CCL4 and TGFβ1 and β2 increased OR for breast cancer at the age ≤ 50 years group." (PMID 38541912, 2024).
breast carcinoma (continued). "Bioinformatics analysis of in silico publicly available TNBC data identified BCL3 and BCL2 as well as the following anti-tumour immune response biomarkers as significantly altered in TNBC compared to other breast cancer subtypes: GZMA, PRF1, CXCL1, CCL2, CCL4, and CCL5." (PMID 38022682, 2023). "In contrast, CCL4/MIP-1β expression is not increased by chronic hypoxia in cultured breast cancer cells, hepatocellular carcinoma or, lung adenocarcinoma." (PMID 32781743, 2020). "Breast cancer cell-derived supernatant treated neutrophils significantly expressed high levels of interleukin-1β (IL-1β), CC-chemokine ligand-2-4 (CCL2, CCL3, CCL4), inducible nitric oxide synthase (iNOS), and matrix metallopeptidase-9 (MMP9), and formed extracellular traps (NETs)." (PMID 33049964, 2020). "Our data showed overexpression of proinflammatory factors including CXCL1, CXCL2, CXCR4, CCL3, CCL4, IL-8, and PTGS2/COX-2 in the peripheral blood of patients with breast cancer both when considering the subtypes individually and when considering all breast cancer samples as a group." (PMID 26884644, 2016). "Additionally, many markers we observed that defined our monocyte clusters (FABP5, FN1, IL1RN, CCL3, CCL4, CXCL8, CXCL3, IL1B) during transient, short-term CM stimulation, were elevated in either PD-L1pos or PD-L1neg TAMs isolated and sequenced from breast cancer." (PMID 40176808, 2025). "Intriguingly, CathD has also been shown to selectively degrade macrophage inflammatory protein (MIP)-1α (CCL3), MIP-1β (CCL4), and SLC (CCL21) that, in turn, may affect the generation of the anti-tumoral immune response, the migration of human breast cancer cells, or both processes." (PMID 26610586, 2015).
viral infection (37 papers, 2009 to 2025). "Several studies demonstrated earlier that the expression of chemokines, such as Ccl2, Ccl3, Ccl4, Ccl5, and Cxcl10, during viral infection is associated with enhanced trafficking of leukocytes into the brain." (PMID 34379515, 2021). "Using two models (glucose treatment and virus infection), we revealed that the chemokine CCL4 was affected by glucose metabolism and ALV-J infection." (PMID 37333648, 2023). "In contrast, this increased expression of CCL4 was subsequently reduced with increasing levels of viral infection in 30-day-old chickens." (PMID 37333648, 2023). "Given that the epithelium influences leukocyte recruitment during viral infection through chemokine signaling, we evaluated the expression of Ccl2, Ccl3, and Ccl4 in lung homogenates from PBS-treated and RSV-infected mice." (PMID 33187989, 2021). "Several chemokines were also involved in response to viral infection (CCL4, CCL11, CXCL10), bacterial infection (CCL2, CCL3, CXCL10), as well as to toxic substances insults (CCL3, CCL4)." (PMID 32295518, 2020). "In total 20 ISGs were significantly upregulated in the RSV-infected mice compared to the non-infected mice and some of the top 10 upregulated genes, such as Irf7,Cxcl10, Ccl2, and Ccl4, are all ISGs known to be induced in response to viral infections." (PMID 33363532, 2020). "Further, and more importantly, restoration of ccl4 expression was able to rescue localization of Ly6C+ inflammatory monocytes to foci of virus infection in IFNαR-/- mice." (PMID 31603920, 2019). "In mild persistent asthmatics, viral infection was associated with increased protein abundance of CXCL10, sICAM-1, CCL2, CCL4, CCL5, CCL20 and CCL24." (PMID 30463560, 2018). "Also, a transcriptome study of neuron cultures after viral infection detected upregulation of Ccl4, Cxcl10, Oas1, Irf1, and Irf7, an important modulator of the type I interferon process." (PMID 38189117, 2024). "The current study addressed whether the established dialog between the chemokine CCL4 and glucose metabolism is involved in virus infection." (PMID 37333648, 2023). "The chemokine CCL4 is necessary for the control of viral infection." (PMID 37333648, 2023). "The interaction between viral infection and CCL4 approached statistical significance." (PMID 30463560, 2018). "CCL-3 and CCL-4 are known to be involved in responses to certain viral infections, but, in addition to macrophage activation, they can drive cell proliferation and may encourage viral propagation such as in Epstein-Barr B-cell infection." (PMID 25323767, 2014). "Moreover, the Tryptophanyl-tRNA Synthetase encoding WARS1, which stimulates immunity against viral infection, chemokines CXCL11, CCL4 and CCL4 receptor CCR5 were also significantly downregulated in low viral load positive old samples compared to age matched control." (PMID 32511341, 2020). "The proinflammatory monocytes (cluster 4) expressed a special gene combination, namely, chemokine ligands, interleukins, as well as lncRNAs (e.g., CCL3L1, CCL4, CCL4L2, CXCL2) related to virus infection, inflammation, and pyroptosis." (PMID 39473904, 2024). "We validated this finding through RT-qPCR, confirming that the expression of the proinflammatory factors IL-1β, CCL4, TNF and CXCL8 decreased progressively with viral infection." (PMID 36544767, 2022). "Chiefly amongst these, CCL3 (macrophage inflammatory protein-1α; MIP-1α), CCL4, CCL5, CXCL8, and CXCL10 are broadly expressed in the context of several (murine/human) viral infections." (PMID 34835105, 2021). "The levels of either gene expression or cytokine proteins (IL-1α, TNFα, IL-6, CXCL10, CCL5, CCL2, CCL3, CCL4, and CCL5) in RSV-infected PMФ are comparable to the H5N3 virus infection." (PMID 28558796, 2017). "At day 2 postinfection, both TNF-α and IL-6 transcripts were moderately induced by wild-type virus, while CCL2, CCL4, CXCL9, and CXCL10 mRNA levels were all highly elevated by wild-type virus infection." (PMID 29138302, 2017).